BDNF (brain derived neurotrophic factor)
Diseases named in the same sentence as BDNF in open-access papers (continued):
Sharing a sentence is not in itself a finding about the gene and the disease.
depression (continued). "Smaller hippocampal volumes have also been reported in BDNF Val66Met-variant carriers, suggesting a genetic association between the BDNF Met variant, hippocampal shrinkage, and the risk of depression." (PMID 34577589, 2021). "In postpartum of a brain sample of a depressed patient, reduced level of hippocampal BDNF was seen, which cause atrophy of the hippocampus and also makes it a prominent biomarker in depression etiology." (PMID 34944471, 2021). "Our work first reveals that Pdcd4 selectively repressed the translation of variant IIc BDNF mRNA, which is involved in depression." (PMID 32203159, 2021). "A significant number of studies have shown an association between the BDNF-p75 pathway and psychiatric symptoms such as anxiety, depression and irritability, while very few studies have shown an effect of this pathway on epileptogenesis." (PMID 34899313, 2021). "Studies that focused on gene-environment interactions in stress resilience reported associations between susceptibility to life stressors and risk alleles, especially 5-HTTLPR and BDNF on depression." (PMID 34492034, 2021). "Stress-induced depression-like behaviours in rodents are associated with increases in proinflammatory cytokines but also with decreases in BDNF and neurogenesis." (PMID 34836413, 2021). "A recent study showed that over-expression of hippocampal FXR causes depression-like symptoms and reduces BDNF expression in the hippocampus in naïve rats." (PMID 33809367, 2021). "MiR-221 has been identified to be closely associated with the progression of depression via targeting the Wnt2/CREB/BDNF axis in hippocampal neurons in a CUMS model." (PMID 33927285, 2021). "Lower expression AMPAR, impaired mTOR complex signaling pathway, and lower level of brain-derived neurotrophic factor (BDNF) is linked to neuronal atrophy and depression." (PMID 33679340, 2021). "We measured serum concentrations of serotonin, brain-derived neurotrophic factor, and ATP, which are associated with the development of depression." (PMID 34567219, 2021). "Dysregulation of BDNF levels, along with the BDNF Val66Met polymorphism (rs6265) have been implicated in neuropsychological disorders such as depression, Alzheimer’s disease, dementia and CRCI." (PMID 33985854, 2021). "In an animal model of depression induced by chronic mild stress, treatment with musk relieved depression-like behaviour, which was associated with an increase in BDNF expression in the hippocampus." (PMID 34063646, 2021). "Chan and Ye in their review emphasized the importance of gender, suggesting BDNF content in certain parts of the brain and the tendency to develop BDNF-deficient diseases, such as depression, to be higher in females." (PMID 33804468, 2021). "In turn, it has been suggested that physical activity causes an increase in the brain-derived neurotrophic factor (BDNF), and this increase is associated with a reduction in levels of anxiety and depression." (PMID 34969395, 2021). "Functional polymorphisms of the BDNF gene are significantly associated with the risk of developing depression after exposure to stressors, and depression is associated with a modest but significant decrease in serum BDNF levels compared with healthy controls." (PMID 34575041, 2021). "Preclinical studies have shown that bilateral ovariectomy as an effective depression model induced by estrogen deficiency significantly decreased BDNF levels in the hippocampus and PFC." (PMID 33628219, 2021). "The literature reveals a tight association between depression phenotype and decreased BDNF content, as well as its reversal by antidepressant when investigated in different stress-induced rodent models of depression." (PMID 34421682, 2021). "Overall, this review reveals associations between changes in serum BDNF levels and depression following stroke." (PMID 34141514, 2021).
depression (continued). "Individual compounds from flavonoids and carotenoids have been tested for mechanisms in important drug targets, MAO (MAOA and MAOB) and BDNF, which are known to be associated with depression through molecular docking studies for possible inhibitory roles." (PMID 35052561, 2021). "Polymorphisms in BDNF were found to be a modifying factor in cases of depression in children, as well as in incidents of depression in elders." (PMID 34573321, 2021). "There was a significant positive association between depression severity, hopelessness, impulsivity, and BDNF methylation status at baseline." (PMID 34640441, 2021). "Alterations in histone methylation in the promoter region of BDNF by stress were associated with depression-like behaviors in mice." (PMID 34577589, 2021). "Herein, we provided strong evidence that Pdcd4 deficiency conferred resilience to CRS-induced depression-like behaviors in mice via increasing mTORC1-regulated BDNF protein level and maintaining of synaptic plasticity in the hippocampus." (PMID 32203159, 2021). "BDNF and its receptor TrkB have been consistently implicated in theaetiology of depression and mechanism of action of currentantidepressants." (PMID 33155503, 2021). "The authors also indicated that such a relation exists not only between depression and BDNF polymorphism, but also between other health disorders, such as stroke, cancer, and subsequent depressive states." (PMID 34573321, 2021). "Decreased levels of BDNF are associated with the development of major depressive disorder, and its increase following antidepressant therapy is measured as a response to therapy criteria in humans." (PMID 34867778, 2021). "The brain-derived neurotrophic factor (BDNF) is a protein associated with major depressive disorders and stress situations." (PMID 33530512, 2021). "BDNF is essential for adult synaptic plasticity and its pathway is associated with major depression and posttraumatic stress disorder." (PMID 34330919, 2021). "Current antidepressants increase BDNF expression in brain regions strongly implicated in depression, such as the hippocampus, and the actions of antidepressants are blocked in BDNF-mutant mice." (PMID 33771970, 2021). "It has been demonstrated that increased DNA methylation of the brain-derived neurotrophic factor (BDNF) gene, encoding the protein responsible for neuronal growth, differentiation and plasticity, is connected with depression in the human population." (PMID 33804455, 2021). "BDNF, a polypeptidic factor, is implicated in the pathophysiology and therapeutic mechanism of depression." (PMID 34207497, 2021). "Further, higher BDNF levels were associated with lower depression ratings after administration of ayahuasca." (PMID 33059356, 2021). "The decline of hippocampal BDNF level caused by inflammatory activation is another pathological basis for depression." (PMID 35155523, 2021). "On the other hand, BDNF hippocampal alterations related to depression seem to be preferentially associated with cognitive rather than emotional symptom dimensions." (PMID 34959434, 2021). "FMTs from patients with IBD/D+ also caused anxiety-/depression-like behaviors, increased the NF-κB+/Iba1+ and lipopolysaccharide (LPS)+/Iba1+ cell populations, and decreased the BDNF+/NeuN+ cell population in the hippocampus." (PMID 34650107, 2021). "BDNF is a critical neurotrophic factor that has been associated with the pathophysiology of depression." (PMID 33112507, 2021). "At the molecular level, the brain-derived neurotrophic factor (BDNF) is another common protein to be associated with decreased depression." (PMID 34007290, 2021). "Among the gene candidates involved in elevated risk for depression, BDNF is particularly interesting since it is involved in neuronal survival, differentiation, and synaptic plasticity." (PMID 34618883, 2021).
depression (continued). "Previous studies demonstrated that increased DNA methylation in the promoter region of BDNF was associated with the pathophysiology of depression." (PMID 33815064, 2021). "Depression risk/recovery was reported to depend on a functional single nucleotide polymorphism (SNP) in BDNF (rs6265; G to A polymorphism encoding a valine (Val)-to-methionine (Met) substitution at codon 66 (Val66Met))." (PMID 33430399, 2021). "Brain-derived neurotrophic factor (BDNF) is a neurotrophin that has been implicated in the pathophysiology of depression and the mechanisms of action of antidepressant drugs." (PMID 33106599, 2021). "It is also important to note that other factors such as tropomyosin receptor kinase B (TrkB) in the BDNF - pCREB pathway have been previously associated with depression." (PMID 33643190, 2021). "Several studies have demonstrated the relationship between BDNF and morphological changes caused by hippocampal neurogenesis dysfunction in patients with depression." (PMID 34577589, 2021). "Previous studies showed that depression-like behaviors are associated with impaired synaptic transmission in the hippocampus and mPFC40–42, and BDNF is an important regulator of synaptic transmission." (PMID 33627628, 2021). "Specific findings have been reported: for example, a study reported a link between the BDNF rs6265 allele (A) and major depressive disorder." (PMID 34942936, 2021). "In a study of patients with refractory epilepsy, polymorphisms in the brain-derived neurotrophic factor (BDNF) gene were associated with depression, whereas alterations in the catechol-omethyltransferase (COMT) gene were associated with anxiety disorders." (PMID 34917019, 2021). "Research has shown associations between depression and BDNF (as well as candidate SNPs of the BDNF gene, polymorphisms of the BDNF gene, and the interaction of these polymorphisms with other determinants, such as stress)." (PMID 34942936, 2021). "Because BDNF and 5-HT, which is reduced by depression, is an important protein involved in neuroplasticity and hippocampal neurogenesis, low serum BDNF and 5-HT levels have been reported to be a risk factor for AD." (PMID 34881077, 2021). "Taken together, these findings suggest that decreased BDNF levels in the hippocampus are tightly linked to morphological alterations and depression pathogenesis in patients." (PMID 34577589, 2021). "Until now, BDNF Val66Met is known to be associated with psychiatric diseases, such as schizophrenia, major depressive disorders, and CNS diseases, including Parkinson’s disease and Alzheimer’s disease." (PMID 34205595, 2021). "It has been widely reported that depression is associated with a downregulation of brain BDNF levels being regarded as a major target of antidepressant medications." (PMID 34721013, 2021). "PKC also activates cAMP response element binding protein, which causes transcription of many important genes such as brain-derived neurotrophic factor that plays an important role in the pathophysiology of depression." (PMID 33515455, 2021). "BDNF levels, equal or less than 1,251.0 pg/ml has been stated to be linked to depression symptoms during methamphetamine withdrawal." (PMID 33499851, 2021). "The AUC (area under the ROC curve) for detection of depression using BDNF was 0.949, with a diagnostic sensitivity and specificity of 90.7 and 90.9%." (PMID 34776888, 2021). "Here, our study provides a candidate, PPARα, as this protein not only correlates with BDNF biosynthesis and neuroplasticity but also is implicated in the pathogenesis of depression." (PMID 34211395, 2021). "At the molecular level, abnormal levels of brain-derived neurotrophic factor (BDNF) have been associated with depression with a higher incidence in women than men." (PMID 34685740, 2021). "These authors also looked at childhood adversity, because it has been reported to increase depression susceptibility by interacting with BDNF genetic variations." (PMID 33430399, 2021).
depression (continued). "There also seems to be a strong link between increased inflammation and impaired neurogenesis associated with decreased BDNF expression in the brain, adding to the association between inflammation, neurogenesis and depression." (PMID 33805073, 2021). "Brain-derived neurotrophic factor (BDNF) is a protein that is implicated in the pathophysiology of depression." (PMID 33801688, 2021). "BDNF is associated with the aetiopathology of mood disorders such as anxiety, depression, and stress-related disorders." (PMID 34646421, 2021). "Attenuations in serum levels of the growth factor BDNF have been linked to depression, and importantly, to antidepressant response." (PMID 33567631, 2021). "A methionine (Met) substitution for valine (Val) at the codon 66 of BDNF (BDNFVal66Met), identified in humans, has been associated with risk for depression and a variety of other neuropsychiatric disorders." (PMID 34618883, 2021). "These subjects also showed atrophy of neurons in the PFC, suggesting that downregulation of BDNF signaling was strongly associated with atrophy of the PFC in patients with depression." (PMID 34577589, 2021). "It is possible that the use of antidepressants is associated with the elevated levels of BDNF in serum in patients suffering from depression." (PMID 34573069, 2021). "BDNF in the hippocampus has been implicated in the pathophysiology of depression and the therapeutic mechanisms of antidepressant treatments." (PMID 33106599, 2021). "Meanwhile, a previous study has reported that reduced BDNF has been implicated in depression, and fluoxetine, a selective serotonin-uptake inhibitor, exerts antidepressant effects through the ERK-CREB signaling system." (PMID 34439529, 2021). "Both RCTs that measured BDNF used the same probiotic strains (L. helveticus + B. longum), which have previously been linked to BDNF increases in a mouse model of depression." (PMID 33567631, 2021). "The BDNF polymorphism moderated the correlation between depression severity and the FA values in UF (p = 0.02)." (PMID 34760029, 2021). "A decrease in BDNF expression is closely associated with menopause-related anxiety, depression, and cognitive deterioration." (PMID 34025413, 2021). "This study showed a similar pattern of both free and total BDNF in association with the characteristics of all groups of patients, particularly pain, depression, and anxiety." (PMID 33915758, 2021). "Stress and depression reduced the expression and function of BDNF, and the antidepressants increased BDNF expression and blocked the growth factor expression deficits caused by stress and depression." (PMID 35010973, 2021). "BDNF has been widely implicated in depression disorders, and zinc activation of GPR39 leads to increased BDNF via the Gαs pathway and CRE-dependent transcription." (PMID 34360964, 2021). "According to modern conceptions, BDNF-TrkB signaling associated with the neuroplasticity maintenance plays a core role in the pathogenesis and treatment of depressive disorder." (PMID 33578683, 2021). "Low levels of BDNF have been suggested to be associated with suicidality in patients with depressive disorders." (PMID 34576215, 2021). "Recent clinical studies have also demonstrated an association between low levels of BDNF and depressive disorders." (PMID 34833132, 2021). "Depressive disorder is associated with marked reduced levels of BDNF, both in humans and different animal models including chronic unpredictable mild stress (CUMS) paradigm." (PMID 34299103, 2021). "Our results suggest that BDNF or SLC6A4 genes profile methylation is independently associated with depressive disorders in patients with epilepsy." (PMID 34912196, 2021). "In the association between the neuroimmune system and depressive disorder, interest has increased in the role of brain-derived neurotrophic factor (BDNF) as well as cytokines." (PMID 34576215, 2021).
depression (continued). "A decreased serum level of BDNF has been associated with insomnia and sleep deprivation, and it has been demonstrated that subjects suffering from current symptoms of depression and insomnia exhibited significantly decreased serum BDNF levels." (PMID 32340112, 2020). "Animal models of depression and psychosocial stress, including social defeat, are associated with increased BDNF levels in the medulla or the forebrain." (PMID 33344701, 2020). "BDNF polymorphism and serum level are related to depression, anxiety, neuroticism and serotonergic neurotransmission." (PMID 32231570, 2020). "During the depression, the role of BDNF can vary; in the hippocampus and the prefrontal cortex, BDNF expression is associated with inhibition of depressive symptoms, whereas it promotes anxiety-like symptoms in the nucleus accumbens and the amygdala." (PMID 33584798, 2020). "Trimethylation of H3K27 has been associated with repressed BDNF exon IV gene expression in a mouse model of depression." (PMID 32012861, 2020). "Alterations in BDNF-TrkB signaling in the brain have been implicated in the pathogenesis of depression and antidepressant mechanisms." (PMID 29882089, 2020). "Carriers of the BDNF rs6265 66Met (A) allele and male sex were predictors of high lethality in suicide attempts in 120 patients with major depressive disorder (MDD)." (PMID 32157595, 2020). "BDNF is one of the most inspiring molecules to better understand the disadvantageous synaptic learning underlying the etiology of depression, accompanied by declines in the rate of adult neurogenesis and in spine densities." (PMID 33096634, 2020). "Another study examined the direct and interactive effect of the BDNF Val66Met polymorphism, depression, and physical exercise in predicting cognitive functioning in the NHRVS genetics subcohort." (PMID 33362593, 2020). "Of note, BDNF prevented the development of aging-associated metabolic decline and reduced anxiety- and depression-like behavior." (PMID 32655354, 2020). "One of the mechanisms underlying depression includes decreased levels of monoamine neurotransmitters (norepinephrine, dopamine, and serotonin) and brain-derived neurotrophic factor in the hippocampus and prefrontal cortex." (PMID 33584294, 2020). "It has been reported that these genetic variations of BDNF play an important role in susceptibility to depression related to AD." (PMID 33269104, 2020). "We did not reproduce this finding concerning BDNF levels but observed an association between BDNF rs6265 and the severity of depression." (PMID 32116853, 2020). "Many studies have shown that BDNF is implicated in the pathophysiology of depression and antidepressant efficacy." (PMID 32513185, 2020). "The combination of tPA, BDNF, tropomyosin receptor kinase B (TrkB), proBDNF, and p75 neurotrophin receptor (p75NTR) have been suggested as a diagnostic biomarker panel to diagnose depression." (PMID 32153441, 2020). "Low levels of BDNF in the mPFC are associated with the development of depression-like phenotypes including anhedonia in rodents." (PMID 29882089, 2020). "Accumulating evidence has shown that BDNF is implicated in the pathophysiology of depression and the antidepressant effects of exercise." (PMID 32210759, 2020). "A study conducted in Chinese subjects concluded that there is a positive association between BDNF Val66Met polymorphism and comorbid depression in T2D patients where Met allele carriers are susceptible to suffer from depression." (PMID 33269104, 2020). "For example, Nestler and colleagues found that social defeat stimulation can induce social avoidance and anxiety-like and depression-like behaviors in mice and that BDNF levels within the NAc are correlated with susceptibility to this stress." (PMID 32085670, 2020). "BDNF is thought to play a role in intracellular signaling in brain regions associated with depression, including the hippocampus, prefrontal cortex, nucleus accumbens and amygdala." (PMID 32575733, 2020).